VCAN (versican)
Diseases named in the same sentence as VCAN in open-access papers (continued):
Sharing a sentence is not in itself a finding about the gene and the disease.
tumor (continued). "HA and versican are known to regulate migration and invasion of many cell types including tumor cells, hypaxial muscle cells and neural crest cells." (PMID 24147033, 2013). "Our results outline a novel mechanism for hCAP18/LL-37 expression in macrophages is regulated via versican V1 secretion from tumor cells into the microenvironment." (PMID 23424670, 2013). "Nevertheless, DSPGs expression were described to be increased in breast cancer fibroadenoma compared to healthy tissue, and, although the DSPG decorin was present in both healthy and tumor tissue, versican was exclusively detected in tumor samples." (PMID 23984412, 2013). "Both versican and lumican were expressed in the stromal as well as in the epithelial tumor compartment." (PMID 22711178, 2013). "In this regard, recent studies indicate that the positive feedback loop formed by versican and monocyte-lineage cells is critical for inducing certain pathologic conditions, such as tumor invasion and metastasis and the formation of atherosclerotic plaques." (PMID 23845159, 2013). "Both versican and lumican play a role in the formation of tumor-specific ECM that can support cancer cell growth and metastasis." (PMID 22711178, 2013). "Versican accumulation in myoepithelial tumours is related to the early differentiation of the myxoid matrix to cartilage." (PMID 23082892, 2012). "The modulation of selected genes such as BMP7, EpCAM and VCAN entailed an increase in the proteins encoded by them, indicating that high CD157 expression alters tumor cell phenotype." (PMID 22916288, 2012). "In tumours with low (group 1) and high (group 2) versican expression, a significant difference in the expression of E-cadherin was observed between the in situ and invasive areas, with P < 0.0001." (PMID 23082892, 2012). "In summary, the results of this in-vitro study demonstrate that versican enhances tumor cell mobility, invasion, and survival in bone tissues." (PMID 22862967, 2012). "In prior studies, these same authors observed increased versican expression in areas of tumour infiltration." (PMID 23082892, 2012). "Our data reveal that in canine CBMTs, versican expression differs significantly between invasive andin situ areas, suggesting a role for this molecule in tumour progression." (PMID 23082892, 2012). "The carcinomatous cells that invade the stroma are believed to be capable of stimulating fibroblasts to produce versican, which in turn plays a crucial role in tumour progression." (PMID 23082892, 2012). "Ligation of TLR2 by versican appears to be directly involved in the activation of multiple types of cells in tumor stroma and the induction of inflammatory cytokine secretion." (PMID 22837669, 2012). "Our data reveal that in CBMTs, versican expression differs significantly between invasive and in situ areas, suggesting a role for this molecule in tumour progression." (PMID 23082892, 2012). "For instance versican, by binding to type I collagen, tenascin-R, fibulin-1, fibulin-2, fibronectin and fibrillin-1, cross-links these matrix components which facilitates tumor invasion and metastasis." (PMID 24213471, 2012). "On the other hand the elevated expression of versican in the tumor stroma was strongly correlated with higher tumor grade and invasiveness in patients with MD and MAMCs." (PMID 21791066, 2011). "The formation of a pericellular matrix rich in HA and versican by vascular SMCs and tumor cells can be inhibited following treatment with HA oligomers." (PMID 21541039, 2011). "Versican was specifically accumulated in MD and MAMCs in the presence of malignant transformation and was significantly correlated with increased tumor grade and invasiveness." (PMID 21791066, 2011). "It is of interest to note that expression of the chondroitin sulfate proteoglycan, versican, which is generally thought to have a tumor-promoting effect, trended lower (p = 0.057) in the n-3 PUFA-enriched Fat-1 tissues." (PMID 21655218, 2011).
tumor (continued). "The increased accumulation of versican in tumor stroma by mammary fibroblasts is correlated with relapse in women with node-negative breast cancer." (PMID 21791066, 2011). "Versican is synthesized mainly by stromal cells and is capable to regulate tumor cell growth and motility." (PMID 21791066, 2011). "Possibly estrogens mainly produced locally by stromal fibroblasts in early stages of breast carcinogenesis drive through paracrine action tumor growth and through autocrine mechanisms the biosynthesis of versican and decorin by themselves." (PMID 21791066, 2011). "With its effects on tumor cell proliferation and migration, versican has been shown to increase the resistance of cancer cells to apoptosis." (PMID 22096483, 2011). "The results of this study suggest that the accumulation of versican in the tumor stroma is correlated with high MD and the formation of MAMCs associated with malignant transformation." (PMID 21791066, 2011). "There is a desire to improve our understanding of the cellular mechanisms involved in versican G3 mediated tumor growth and invasiveness." (PMID 22096483, 2011). "Versican, a large extracellular matrix proteoglycan, accumulates both in tumour stroma and cancer cells." (PMID 20871832, 2010). "There is increasing recognition of the importance of versican G1 to tumor growth, motility, and metastasis." (PMID 21079779, 2010). "Although we do not know whether the high expression of EGFR signal is promoted by versican or activitated in association with other molecular determinants, understanding the signaling cascade is important towards the mechanisms of action in factors that influence tumor invasiveness." (PMID 21079779, 2010). "The C-terminal G3 domain of versican influences local and systemic tumor invasiveness in pre-clinical murine models." (PMID 21079779, 2010). "Several upregulated genes (collagen type I, III, V, XI, fibronectin 1, versican) were related to tumor- ECM interactions and focal adhesion." (PMID 17389037, 2007). "The peripheral regions surrounding a tumor appear to have a greater versican expression and the pathways involved in versican-mediated cancerous growth warrants ongoing study." (PMID 17662123, 2007). "Versican-rich extracellular matrices exert an anti-adhesive effect on the tumour cells, thus facilitating tumour cell migration and invasion." (PMID 17453002, 2007). "The importance of versican G3 with its EGF-like motifs on local tumor invasion has been demonstrated in other cancer cell types." (PMID 17662123, 2007). "This was consistent with the observation of increased versican G3 expression as assessed by immunoblotting in the experimental group following tumor tissue harvest when compared to the vector control group." (PMID 17662123, 2007). "The propensity of versican G3 to influence tumor invasion to bone and the mechanisms of G3 mediated osteolysis warrants ongoing studies." (PMID 17662123, 2007). "The propensity of versican G3 to influence tumor invasion to bone and the mechanisms of versican G3 mediated osteolysis warrants ongoing study." (PMID 17662123, 2007). "Versican expression has been observed in both tumor and stromal cells although the relative extent varies amongst different cancer cell types." (PMID 17662123, 2007). "The expression of versican by tumor cells appears to relate to higher mitotic activity and a reflection of cell proliferation." (PMID 17662123, 2007). "Consistent with the observation of greater local tumor growth, the G3 domain of versican also influences the development of distal metastasis to bone and soft tissue." (PMID 17662123, 2007). "The increased expression of certain versican isoforms in the extracellular matrix (ECM) plays a role in tumour cell growth, adhesion and migration." (PMID 17453002, 2007). "The cellular mechanisms are not fully understood and this study evaluated versican G3 domain with its EGF-like motifs in influencing tumor invasion and metastasis." (PMID 17662123, 2007).
tumor (continued). "Versican mediated cancerous growth appears dependent on the close interactions between tumor cells and its surrounding stromal components." (PMID 17662123, 2007). "Versican isoforms V0 and V1 are overexpressed in tumours, suggesting that these isoforms are mainly involved in tumour development." (PMID 17453002, 2007). "However, higher levels of versican were observed in CMTs, suggesting that the presence of myoepithelial cells in this tumor type contributes to the stromal composition and promotes increased versican expression." (PMID 40005948, 2025). "Besides these studies on PC cell adhesion and motility-related processes, further articles established the role of VCAN in organization of tumor spheroids, which indicated its role in cancer stem cells’ biology." (PMID 41470114, 2025). "A deeper analysis of the stromal microenvironment and its relationship with immune modulators, such as VCAN, as well as T-cell subtypes might reveal important insights into key differences in the tumor biology of young patients." (PMID 39980836, 2025). "The observed effects of VCAN on cell adhesion, proliferation, and migration could indicate an involvement in angiogenic processes, consistent with tumor data." (PMID 40623650, 2025). "It has been shown that VCAN can exert anti-apoptotic effects by increasing cell adhesion, cell-matrix interactions and the expression of integrin β1 and fibronectin, thereby protecting cells from oxidative stress-induced apoptosis in tumour cells." (PMID 40386063, 2025). "This indicates that VCAN may have a biological role in tumour immunology, especially in the signaling pathways related to immune checkpoints." (PMID 40386063, 2025). "Platelet-derived growth factor (PDGF) and vascular endothelial growth factor (VEGF) produced by tumor cells, and versican (VCAN), an extracellular matrix proteoglycan, are considered to be the important factors involved in pulmonary vascular remodeling seen in PTTM." (PMID 39897287, 2025). "VCAN, exhibiting elevated expression and secretion in tumor cells, advances cancer development." (PMID 39823128, 2025). "Elevated expression of this PG in peritumoural mammary adipose tissue has been linked to enhanced proliferative activity, increased body mass index, and greater tumour aggressiveness, suggesting that versican mediates the metabolic–stromal interplay driving tumour progression." (PMID 41463344, 2025). "To investigate the role of VCAN in tumours, we knocked down VCAN in A431 cells." (PMID 40386063, 2025). "Consequently, versican contributes to various processes occurring at the tumor site, including cellular adhesion, migration, proliferation, apoptosis, and angiogenesis." (PMID 40656954, 2025). "The dysregulation of versican (VCAN) leads to tumor invasion." (PMID 41451347, 2025). "VCAN has the potential to modulate immune infiltration by reducing the immunosuppressive phenotype of immune cells, thus enabling a more efficient anti-tumor response." (PMID 38980810, 2024). "We next investigated whether VCAN-attached CS-GAGs exhibited intraregional sulfation pattern differences throughout the tumor." (PMID 38517140, 2024). "Additionally, CD34, FN1, LOXL2, and VCAN are key players in tumor angiogenesis, invasion, and metastasis." (PMID 39012409, 2024). "Overall, results from the analysis show that inflamed stromal subregions exhibit increased VCAN expression in association with altered CS-GAG sulfation patterning, which may impact immune cell migration into the tumor core." (PMID 38517140, 2024). "Interestingly, ADAMTS-derived cleavage fragments of versican (e.g., versikine) have been shown to modulate key aspects of the tumour immune landscape, including modulation of DCs and CD8+ T-cell recruitment in myeloma, lung cancer, and CRC." (PMID 38791926, 2024). "One possible mechanism through which VCAN influences prognosis is that VCAN overexpression in DLBCL may also impact tumor cell proliferation." (PMID 38980810, 2024).
tumor (continued). "Furthermore, SPP1+ Mφ, cycling Mφ, and DCs exhibited significantly higher content in tumors, while C1QA+ and VCAN+ Mφ were reduced in tumor samples in both the LIHC and LIRI HCC cohorts." (PMID 39691723, 2024). "Overall, we conclude that VCAN can either support or inhibit T-cell trafficking within the tumor microenvironment depending on the pattern of GAGs present, and that VCAN is a major component of the ECM immunologic barrier that defines the type of response to immunotherapy." (PMID 38517140, 2024). "As the ECM is a multitasking agent in cancer dynamics, collagen fibers from areas in situ and invasion were also characterized to better investigate the remodeling of the ECM against VCAN proteolysis in the tumor microenvironment, correlating them to the presence of VKINE." (PMID 39682243, 2024). "Moreover, VCAN enhanced tumor cell resistance to apoptosis and modulated BC cell resistance to chemotherapeutic agents." (PMID 39501160, 2024). "Overall, we concluded that the pattern of VCAN isoforms produced in the tissue were not associating with particular TIPs, and tumor–fibroblast interactions were also not driving a specific pattern of isoforms or altering VCAN expression." (PMID 38517140, 2024). "The significant upregulation of LTA − TNFRSF1B between CD4-C3 and VCAN+ TAMs suggests that VCAN+ TAMs may facilitate tumor immune suppression and proliferation through interactions with Tregs." (PMID 39232806, 2024). "Evidence shows that VCAN is involved in both malignant transformation and tumor progression." (PMID 39554845, 2024). "In TNBC, VCAN is expressed by both tumor cells and fibroblasts." (PMID 38517140, 2024). "Patients with GC from the PRSlow group may be characterized by the infiltration of VCAN-mediated monocytes into the tumor center, where they form macrophages and are polarized to exert an anti-tumor phenotype." (PMID 38773976, 2024). "However, the role of VCAN proteolysis in the modulation of inflammatory cells within the tumor microenvironment, as well as its influence on ECM degradation and potential prognostic significance, remains poorly investigated." (PMID 39682243, 2024). "Furthermore, significantly higher VCAN levels in tumor tissues compared with normal tissues were observed in different RCC cohorts obtained from the TNMplot and GEO (GSE105288, GSE46699, GSE159115) databases." (PMID 39333870, 2024). "In the case of Lewis lung cancer (LLC), the VCAN produced by tumour cells may interact with the TLR2/TLR6 complex to promote metastasis of the lung, liver, and adrenal glands." (PMID 38791985, 2024). "VCAN is an extracellular matrix protein that promotes tumor metastasis, invasion, and growth." (PMID 39018396, 2024). "Additionally, we observed that the association between the PRS and macrophage polarization was limited to the tumor center, possibly because of the presence of VCAN, a constituent molecule of the PRS." (PMID 38773976, 2024). "Given the evidence, enrichment in related pathways reveals that VCAN+ TAMs may be associated with the chronic inflammatory environment in the TME, thus contributing to tumor progression." (PMID 39232806, 2024). "TGF-β signal pathway associated molecules such as versican (VCAN) could also promote CAFs phenotypic transformation by activating the TGF-β pathway, resulting in tumor metastasis." (PMID 36698173, 2023). "Thus, VCAN-driven IKKβ activation mediates NF-κB signaling, IL-1β expression, differentiation, and pro-tumor function of macrophages." (PMID 36980752, 2023). "Moreover, the transcriptomes of the VCAN+ TAMs and C1QC+ TAMs showed gradual differences, suggesting that VCAN+ TAMs were reprogrammed into C1QC+ TAMs in the tumor region." (PMID 37383234, 2023). "In addition, some studies have demonstrated that CD146- and versican (VCAN)-positive CAFs play an important role in tumor growth inhibition." (PMID 37217855, 2023).
tumor (continued). "Fibrogenesis in S‐ECM samples is likely due to the presence of an activated cancer‐associated fibroblast (CAF) population in the tumor microenvironment, as indicated by the identification of CAF marker genes as key regulators for S‐ECM, including FAP, ACTA2, PDGFRB, VCAN, and ITGA11." (PMID 36637997, 2023). "In addition to promoting angiogenesis and tumor growth, the microenvironment can also affect versican expression in tumor cells." (PMID 37259101, 2023). "Additionally, we evaluated the VCAN protein levels in the tissues of LVI(+) and LVI(−) patients by analyzing VCAN tissue staining of five tumor samples from each group." (PMID 37108649, 2023). "Moreover, ECM-related proteins (Col1A, Integrinα-V, Versican, THBS1) were associated with tumor suppression and better outcome in CLL13." (PMID 36899005, 2023). "Conversely, versican secreted by THP-1 cells can ligate TLR-2 on these cells to induce the production of inflammatory cytokines in an autocrine fashion which generates an inflammatory microenvironment congenial for tumor progression." (PMID 37784035, 2023). "It is likely that VCAN works by activating the stroma and remodeling the tumor microenvironment." (PMID 37965470, 2023). "We found that VCAN was mainly expressed in fibroblasts and macrophages rather than epithelial cells, and the expression of VCAN was concentrated in the deep layers of tumor tissues." (PMID 36203562, 2022). "Meanwhile, we hope that specific inhibitors for VCAN could be developed to improve the effect of anti-tumor therapy in the future studies." (PMID 36203562, 2022). "In addition, versican is an immunosuppressive component that is detrimental to patient survival by reducing T-cell infiltration, while core proteoglycan is an anti-tumor component that slows down tumor cell growth." (PMID 36010993, 2022). "VCAN is a large extracellular matrix proteoglycan that accumulates in tumor stroma and plays a key role in malignant transformation and tumor progression, through regulation of cell adhesion, proliferation, apoptosis, migration, angiogenesis, invasion, and metastasis." (PMID 35954429, 2022). "Moreover, the bulk RNA-seq and single-cell RNA-seq data were analyzed to illustrate the role of VCAN in tumor microenvironment." (PMID 36203562, 2022). "Synthesizing our findings and previous studies, we proposed the mechanism hypothesis of VCAN influencing prognosis and anti-tumor treatment response." (PMID 36203562, 2022). "VCAN has major functions in tumor cell growth and metastasis, and in our analysis it is expressed robustly both in localized disease and in metastatic samples, underscoring its likely importance along the entire tumor natural history." (PMID 36371231, 2022). "A study on PCa cell lines also showed that a versican-rich matrix might enable increased tumor cell motility and facilitate local invasion, and thus metastasis." (PMID 36230789, 2022). "Notably, we also found an interaction between HAS1-2 and VCAN, which is an essential proteoglycan supporting growth, survival, angiogenesis, metastasis, migration and invasion of tumour cells." (PMID 35767191, 2022). "Therefore, how VCAN specifically regulates the physiological activities of tumor cells remains to be further explored." (PMID 36523602, 2022). "In addition to its role in cellular migration, it is also possible that versican acts by altering cell adhesion, which contributes to the maintenance of tumor-propagating-like features of CTC clusters and augments their ability to proliferate at distant sites." (PMID 34631514, 2021). "Therefore, we found that VCAN was not only related with tumor immune infiltration, but also an independent factor for the prognosis of GC patients." (PMID 33631054, 2021). "The PPI network also reveals that proteins were related with cell adhesion of the ECM remodeling pathway (DCN, FN1 etc.), suggesting that VCAN may be involved in tumor progression which is an important ECM component through the ECM remodeling pathway." (PMID 33604385, 2021).